DNM2 (dynamin 2)
Diseases named in the same sentence as DNM2 in open-access papers (continued):
Sharing a sentence is not in itself a finding about the gene and the disease.
infection (continued). "The efficiency of trans-infection was lower in the presence of indinavir, but was still significant, and was reduced from 3.5 ± 1.5% to 1.4 ± 0.8% by dynamin-2 depletion and to 1.1 ± 0.6% by IRSp53 depletion, representing effects on transmission of virus originating from the VCC." (PMID 40067817, 2025). "Disruption of CLIC/GEEC pathway or depletion of dynamin-2 in MDMs led to a significant inhibition of trans-infection, consistent with a model in which both pathways contribute to particle uptake and VCC formation, and are therefore required for efficient trans-infection." (PMID 40067817, 2025). "Furthermore, the levels of p-Src, p-p38 MAPK, p-caveolin-1 Tyr14, and dynamin 2 in ARV-infected cells were further increased in cells which were pretreated with CSK inhibitor before infection for 2 h." (PMID 37097149, 2023). "Expression of dynamin 2 (DNM2) and tetraspanin 7 (TSPAN7) in DCs favors maintaining viral particles on the surface of DCs, whereas DCs deficient in DNM2 and TSPAN7 redistributed viral particles in micropinosomes, exhibiting reduced trans-infection ability." (PMID 35802715, 2022). "Furthermore, the wild-type or mutant plasmids of dynamin-2 were transfected into cells, followed by incubation with Tfn or infection with PDCoV 24 h later." (PMID 35336903, 2022). "HAdV26 infection in the A549 cell line is partially dynamin-2-dependent." (PMID 35924932, 2022). "Furthermore, we challenged the immune system of Dnm2 wt/K562E and control mice with infection by Listeria monocytogenes and analysed immune cells in blood, spleen, bone marrow and peritoneal cavity compartments." (PMID 32129442, 2020). "Consistent with the results of these two studies, another study showed that the silencing of caveolin-1 in HepG2-NTCP cells did not decrease HBV infection, whereas the silencing of CHC, dynamin-2 (DNM2), and AP-2 resulted in a very large decrease in the level of infection." (PMID 32570893, 2020). "Nevertheless, there is growing interest in the field to understand the role of actin dynamics in HIV infection: a recent report (Ménager and Littman, 2016) points at the importance of DNM2 in dendritic cells mediated trans-enhancement of CD4 T cell infection by HIV in vitro." (PMID 28076788, 2017). "Since Rac1 is important to ASFV entry, we have analyzed whether dynamin-2 pathway plays a role either in ASFV entry or infection." (PMID 22719252, 2012). "Our studies showed that a DN mutant of the ‘aa’ splice variant of dynamin-2 does not inhibit BTV-1 uptake or infection of BHK cells." (PMID 20613878, 2010). "MDMs were infected with HIV-1BaL and treated with control siRNA or dynamin-2 siRNA, and VCC formation evaluated on day 12 post-infection." (PMID 40067817, 2025). "These endocytic fusion events are likely culminating inproductive infection since endocytic inhibitors, such as EIPA, Pitstop2,and Dynasore, as well as a dominant-negative dynamin-2 mutant, inhibitedHIV-1 infection in HeLa-derived and primary CD4+ T-cells." (PMID 37589658, 2023). "Here we report that infection of primary neuronal cultures with HSV-1 triggers Src tyrosine kinase activation and subsequent phosphorylation of Dynamin 2 GTPase, two players with a role in GA integrity maintenance." (PMID 28879169, 2017). "Both siRNAs downregulating clathrin-mediated endocytosis-associated proteins, such as clathrin heavy chain (CLTC) and Dynamin 2 (DNM2), and agents affecting this uptake pathway (Chlopro, Dynasore, Dyngo-4a) were capable of inhibiting infection with MHV." (PMID 25375324, 2014). "In the absence of indinavir, infection percentage was reduced from 6.8 ± 3.1% to a mean of 3.3 ± 1.2% following dynamin-2 depletion, and to 1.9 ± 1.1% following IRSp53 depletion, representing transmission of both newly-formed virus and virus from the VCC." (PMID 40067817, 2025).
infection (continued). "The results of western blot and gray scale analysis showed that BoHV-1 increased the expression of p-caveolin-1, CHC, and dynamin-2 at the initial infection stage, while not affecting the expression of caveolin-1, which was consistent with the report." (PMID 39104584, 2024). "Individual guides were transduced into Cas9-expressing RAMOS cells at low multiplicity of infection, including positive control guides targeting DNM2 and non-targeting guides." (PMID 36849510, 2023). "Our data provide insight into quite interesting nature of HAdV26 infection pathway suggesting that depending on the receptor status this virus can enter the cell in different manner which can be independent of dynamin-2, clathrin and/or caveolin-1." (PMID 35924932, 2022). "Here we demonstrated that HAdV26 infection involves dynamin-2 regardless of cell lines used for analysis, i.e., decreased expression or inhibited function of dynamin-2 decreased both internalization and transduction efficiency of HAdV26." (PMID 35924932, 2022). "Therefore, under normal infection conditions SopD-mediated inactivation of Rab10 may have the dual benefit of i) releasing Rab10-mediated stabilization of plasma membrane invaginations and ii) simultaneously promoting recruitment of Dynamin-2 via its ability to bind GDP-bound Rab10." (PMID 34349110, 2021). "Treatment with a dynamin-2 inhibitor, dynasore, also impaired PCV3 infection." (PMID 33679671, 2021). "The results showed that although the level of jam-a and caveolin-1 expression did not change significantly during the infection, the expression of ap2m1 and dynamin-2 in the various tissues exhibited significant changes." (PMID 30326628, 2018). "To examine the roles of clathrin-dependent endocytic pathway in the enhancement of EV71-infection by CPZ, we performed siRNA knockdown of the AP2M1, CLTC, DNM2 and FCHO2 (the reported crucial CME components) in A549 and RD cells and tested the viral infectivity with additional CPZ treatment." (PMID 29298696, 2018). "Thus, while Eps15, dynamin-1, dynamin-2, dynamin-3, and clathrin heavy chain siRNAs inhibited HMPV entry and diminished infection, cells that did become infected exhibited normal amounts of surface F protein." (PMID 26629703, 2015). "Dynasore, a noncompetitive inhibitor of dynamin-2, reduced infection of SFV and SV40 to 30% and 40%, respectively." (PMID 22536154, 2012). "Suppression of endocytosis by a dynamin GTPase inhibitor, dynasore, or by siRNA-mediated knockdown of dynamin 2 expression attenuated the MLV infections in all cells examined (including XC cells), showing that these infections occur through endosomes even in XC cells." (PMID 22022555, 2011). "The knockdown of dynamin 2 expression by siRNAs did not affect the VSV-G-pseudotyped vector infection." (PMID 22022555, 2011). "Although virus entry and infection were not inhibited by the dominant-negative dynamin-2 mutant, entry was inhibited by the general dynamin inhibitor, dynasore, indicating that virus entry is dynamin dependent." (PMID 20613878, 2010). "We found no inhibitory effect on infection efficiency when dynamin-2 was depleted with siRNA, or when we expressed the dn Dyn2K44A-mutant." (PMID 18836553, 2008). "Additionally, MDBK cells incubated with BRSV at 4°C for 1 h were transferred to 37°C for 30 min, the localization of dynamin-2 and BRSV G protein was analyzed by IFA and confocal microscopy, the result showed clear co-localization of dynamin-2 and G protein after 30 min of infection." (PMID 38690369, 2024). "Regardless of αvβ3 integrin expression, HAdV26 infection involves dynamin-2." (PMID 35924932, 2022). "Some factors identified in our screen might have been predicted: AP2M1 and DNM2, two components of the endocytic pathway were identified in the primary screen to restrict infection of cells by the pseudovirus but not by wild type HIV-1 viruses." (PMID 22082156, 2011).
infection (continued). "Thus, the inhibitors and the siRNA-mediated dynamin 2 knockdown did not attenuate the MLV vector infections by suppressing MLV particle binding to the target cells." (PMID 22022555, 2011). "Here we report that BTV-1 infection of BHK cells is also dependent on a low endosomal pH; however, virus entry and infection were not inhibited by dominant-negative mutants of Eps15, AP180 or the ‘aa’ splice variant of dynamin-2, which were shown to inhibit clathrin-mediated endocytosis." (PMID 20613878, 2010).
myopathy (32 papers, 2009 to 2026). A disease of the muscle in which the muscle fibers do not function properly. "In this report, we present the case of a 47-year-old man affected with DNM2-related myopathy associated with a novel missense variant in the PH domain of dynamin-2." (PMID 40259930, 2025). "Reduction of DNM2 in Speg-KO mice was associated with an increased life span, improved body weight, amelioration of motor behavior, and alleviated myopathy-associated pathological features." (PMID 35763354, 2022). "DNM2-related myopathies are the consequence of a missense mutation in the dynamin 2 (DNM2) gene, leading to an autosomal congenital dominant disease." (PMID 33255644, 2020). "This study confirms the epistasis between Mtm1 and Dnm2 and the ‘cross-therapy' rationale that targeting another myopathy gene (DNM2) than the one mutated in the disease (MTM1) can efficiently re-balance muscle function." (PMID 28589938, 2017). "Plasma membrane permeability to calcium appears involved in the pathophysiology of the myopathy related to DNM2 mutation." (PMID 27870637, 2016). "Autosomal dominant mutations in DNM2, the gene encoding dynamin 2, another membrane trafficking protein, also cause myopathy resulting in both mild and severe forms of disease." (PMID 26325203, 2015). "Dynamin-2 is a widely ubiquitously expressed GTPase whose mutations cause severe hereditary neuropathies and myopathies in humans." (PMID 23940613, 2013). "Pathogenic variants of DNM2 were known to cause myopathy and Charcot–Marie–Tooth disease." (PMID 36619507, 2022). "To assess whether the differentially regulated transcripts can expand the knowledge about the cellular and molecular phenotype of Dnm2 wt/K562E muscles, or even suggest potential causes of the myopathy, we performed Gene Ontology (GO) analysis using EnrichR." (PMID 32129442, 2020). "Although we cannot exclude mouse-specific effects of the Dnm2 K562E allele on skeletal muscles, there are some hints that a primary myopathy might contribute to CMTDIB disease also in humans." (PMID 32129442, 2020). "Moreover mutations in DMN2 result in severe hereditary neuropathies and myopathies in humans, strongly suggesting that dynamin-2 has more susceptible functions in the nervous and skeletal muscle tissues." (PMID 24065954, 2013). "A.R.F. has been a member of an independent data monitoring committee for a different clinical trial for MTM1-related myopathy and DNM2-related myopathy (the trial was terminated early)." (PMID 40979471, 2025). "First, we reported 18 novel variations in 6 myopathy-causing genes, including RYR1, NEB, ACTA1, DNM2, TTN and TNNT1, and we described the clinical discrepancy between our patients and previous reports, especially in RYR1- and TNNT1- related myopathy." (PMID 35081925, 2022). "In fact, BIN1- and DNM2-related myopathies affect the skeletal muscular triad, while the heart has dyads and would thus be less affected." (PMID 36140701, 2022). "Taken together, these observations in the mutant TA recapitulate key myopathic features of the mutant soleus muscle and confirm that the myopathy in Dnm2 wt/K562E mice affects multiple skeletal muscles." (PMID 32129442, 2020). "The myopathy was accompanied with mitochondrial dysfunction, which can be attributed partly due to the upregulation of DNM2." (PMID 33255644, 2020). "Here we show that systemic delivery of Dnm2 antisense oligonucleotides (ASOs) into Mtm1KO mice efficiently reduces DNM2 protein level in muscle and prevents the myopathy from developing." (PMID 28589938, 2017). "Congenital myopathies with mislocalized nuclei include CNMs and are genetically heterogeneous diseases caused by mutations in at least seven genes (MTM1, DNM2, BIN1, RYR1, TTN, SPEG and ZAK), with MTM1, DNM2, BIN1 and RYR1 being the most frequently associated." (PMID 41459639, 2025). "This study expands the clinical and genetic repertoire of DNM2-related myopathy." (PMID 40259930, 2025).
myopathy (continued). "Our results indicate that these myopathic features in Dnm2 wt/K562E mice are caused by the Dnm2 K562E allele, since we found no evident signs of a myopathy in Dnm2 wt/0 mice, consistent with a previous complementary analysis." (PMID 32129442, 2020). "Our analysis thus far had revealed a mild but definitive myopathy in Dnm2 wt/K562E mice." (PMID 32129442, 2020). "In contrast, Dnm2 wt/K562E mice were affected by a mild but definitive and lasting myopathy." (PMID 32129442, 2020). "The observation of myopathic features in the soleus muscles of Dnm2 wt/K562E mice prompted the question of whether the myopathy is restricted to this muscle." (PMID 32129442, 2020). "Our morphological assessment points to a primary myopathy-like phenotype in Dnm2 wt/K562E mice." (PMID 32129442, 2020). "Evaluations of the distributions of fibre diameter frequencies in haematoxylin-eosin (H&E)-stained soleus muscle cross sections revealed a shift towards smaller-calibre fibres in Dnm2 wt/K562E mice compared to control mice at both ages, suggestive of a myopathy." (PMID 32129442, 2020). "However, subsequent studies have identified several DNM2 mutations as a cause of neonatal-onset severe muscle weakness, thus expanding the spectrum of DNM2-related myopathies to include essentially all ages and ranges of severity." (PMID 30426359, 2018). "Tamoxifen might also prove useful in other myopathies where t-tubule defects secondary to increased DNM2 levels contribute to the pathogenesis, such as BIN1-related CNM and caveolin-3 and dysferlin-related myopathies." (PMID 30451843, 2018). "Although most dynamin-2 mutations linked to CMT and CNM are located in the middle and PH domains, there are no common mutations to both disorders and the molecular mechanisms that lead to the neuropathy or myopathy remain obscure." (PMID 24065954, 2013). "Importantly, a dose–response effect was observed, with higher doses resulting in a more rapid improvement of the disease phenotype, thus validating the disease severity model generated, and confirming a reduction of the myopathy features in a dose–response manner following Dnm2 reduction." (PMID 35642830, 2022). "Of the DNM2‐CNM patients, 61% had family members with a diagnosed myopathy; in MTM1 and RYR1 patients this was the case in 50% and 44%, respectively." (PMID 34463354, 2021). "With regard to the human disease caused by the analogous genetic mutation, we asked whether the presence of a single wild-type Dnm2 allele alone, i.e. haploinsufficiency without a necessary contribution by the Dnm2 K562E allele, is sufficient to cause a myopathy, at least in mice." (PMID 32129442, 2020). "Although DNM2 reduction rescued the myopathy phenotype, it did not improve cardiac dysfunction, indicating a differential tissue-specific function." (PMID 35763354, 2022). "Of note, exon 7 inclusion in BIN1 promoted binding to DNM2, again suggesting that the interplay between BIN1 and DNM2 is important for normal muscle function and in the setup of the CNM and DM myopathies." (PMID 32994313, 2020). "Reducing DNM2 could increase the life span, body weight, and motor performance of SPEG-deficient mice, thereby rescuing SPEG-related myopathy, but not alleviate the cardiac dysfunction." (PMID 35763354, 2022). "BIN1 acts as a negative regulator of DNM2 activity during muscle maturation and modulation of DNM2 intracellular levels alleviates the requirement for BIN1 since Bin1−/− Dnm2+/− mice were alive and did not suffer from myopathy whereas the Bin1−/− KO mice were not viable." (PMID 32164332, 2020).
neurodegenerative disease (6 papers, 2013 to 2025). A disorder of the central nervous system characterized by gradual and progressive loss of neural tissue and neurologic function. "Other human neurodegenerative disease-related genes sharing a PH/RhoGEF domain, such as DNM2, SBF2, and ALS2, could provide important clues for these elusive questions." (PMID 23844677, 2013).
peripheral neuropathy (6 papers, 2015 to 2021). A disorder affecting the peripheral nervous system. "Interestingly, DNM2 variants associated with peripheral neuropathy are mostly located in the membrane binding PH domain." (PMID 33810506, 2021). "Using loxP/Cre recombination-mediated gene ablation in mice, we found that lack of DNM2 in developing or adult SCs resulted in a severe peripheral neuropathy, characterized by SC loss and signs of inflammation." (PMID 30648534, 2019). "The identification of the DNM2 p.R719W mutation as the cause of HSP in this family brought attention to the fact that mutations in this same gene are responsible for other phenotypes, including two forms of CMT peripheral neuropathy." (PMID 26517984, 2015). "Studies of cell-type specific conditional DNM2 knockout mice provide interesting insight, with Schwann cell knockout resulting in cell death and rapid progression to peripheral neuropathy, while oligodendrocyte knockout does not cause significant effects in the CNS." (PMID 33810506, 2021).
genetic disorder (5 papers, 2018 to 2025). "It has been suggested that mutations in the DNM2 gene, associated with 3 inherited diseases, disrupt endocytosis." (PMID 31017801, 2019). "Consequently, allele‐specific silencing is clearly identified as a promising therapeutic strategy for AD‐CNM, allowing envisions of a treatment for this neuromuscular disorder and in extension to other DNM2‐linked inherited diseases." (PMID 29246969, 2018).
neurologic disease (5 papers, 2011 to 2025). "Zebrafish have been shown to be an excellent animal model for many neurologic disorders, and this system has the potential to inform our understanding of DNM2-related disease." (PMID 23418470, 2013).
neuromuscular disease (4 papers, 2013 to 2023). "As a first step towards developing zebrafish models of DNM2-related neuromuscular disease, this manuscript describes the characterization of two zebrafish dynamin-2 orthologs, as well as the effects of altered gene expression on muscle histology and function." (PMID 23418470, 2013).
cardiac disease (1 paper, 2014). "Our present study provides evidence for the role of DNM2 in ischaemic ventricular arrhythmia, which is a common cardiac disease." (PMID 25092467, 2014).
DNM2 also shares sentences with these, for which no sentence is quoted: Duchenne muscular dystrophy (59 papers); lung carcinoma (5); colorectal cancer (4); dilated cardiomyopathy (4); muscle disorder (4); cervical cancer (3); endometriosis (3); ischemia (3); multiple sclerosis (3); nemaline myopathy (3); spinocerebellar ataxia type 5 (3); Becker muscular dystrophy (2); brain injuries (2); cataract (2); colon cancer (2); fibrosis (2); gastric cancer (2); Hepatic fibrosis (2); Hypertension (2); inflammatory skin disease (2); Larsen syndrome (2); malaria (2); parasite infection (2); schizophrenia (2); tauopathies (2); triple-negative breast carcinoma (2); amyotrophic lateral sclerosis (1); aneurysm (1); Anxiety (1); aortic aneurysm (1).
A further 101 diseases each share a sentence with DNM2 in 1 paper.